TRIM45 (tripartite motif containing 45)
Description:
E3 ubiquitin-protein ligase that plays a role in the regulation of inflammatory response. Mechanistically, mediates the 'Lys-48'-linked polyubiquitination of TAB2, a regulatory protein of the kinase TAK1, leading to its degradation via the proteasomal pathway and inhibition of the TLR-mediated inflammatory immune response. May act as a transcriptional repressor in mitogen-activated protein kinase signaling pathway.
Synonyms: RNF99; FLJ13181
Tractability: PROTAC: ubiquitination databases record sites on it.
Gene: Protein-coding gene on chromosome 1 (117,111,060 to 117,122,587, reverse strand). Ensembl gene ENSG00000134253.
Subcellular location: Cytoplasm; Nucleus
Subcellular location (Human Protein Atlas): Cytosol; Cytokinetic bridge; Nucleoplasm
Pathways (Reactome):
Immune System: Interferon gamma signaling
Gene Ontology:
Molecular function: ubiquitin protein ligase activity; zinc ion binding
Biological process: negative regulation of inflammatory response; proteasome-mediated ubiquitin-dependent protein catabolic process; protein K48-linked ubiquitination
Cellular component: cytoplasm; cytosol; nucleoplasm; nucleus
Genetic constraint (gnomAD): Loss-of-function variants: 44 observed, 49.38 expected, observed/expected ratio (o/e) 0.89, 90% interval 0.7 to 1.15. The upper end of that interval is the gene's LOEUF score, 1.15, which puts it in group 5 of 6, group 1 being the genes least tolerant of losing a copy. Missense variants: 678 observed, 762.11 expected, observed/expected ratio (o/e) 0.89, 90% interval 0.83 to 0.95. Synonymous variants: 258 observed, 302.02 expected, observed/expected ratio (o/e) 0.85, 90% interval 0.77 to 0.95.
Homologues: Orthologues: chimpanzee TRIM45 (98% identical), macaque TRIM45 (97% identical), dog TRIM45 (92% identical), pig TRIM45 (89% identical), mouse Trim45 (86% identical), rat Trim45 (86% identical), rabbit TRIM45 (82% identical), zebrafish trim45 (47% identical). Paralogues in human: TRIM47 (20% identical), PML (16% identical), TRIM39 (15% identical), MID2 (15% identical), TRIM25 (14% identical), TRIM68 (14% identical), TRIM22 (14% identical), TRIM27 (14% identical), TRIM11 (14% identical), TRIM21 (14% identical), TRIM36 (14% identical), MID1 (14% identical), and 68 more.
Diseases named in the same sentence as TRIM45 in open-access papers:
TRIM45 is named in the same sentence as 25 diseases in open-access papers, as found by Europe PMC text mining. Sharing a sentence is not in itself a finding about the gene and the disease. The quoted sentences say what the papers report.
glioma (7 papers, 2017 to 2024). A benign or malignant brain and spinal cord tumor that arises from glial cells (astrocytes, oligodendrocytes, ependymal cells). "This is at odds, however, with the observation that TRIM45 expression levels are reduced in more aggressive gliomas." (PMID 38115822, 2023). "Taken together, these data indicated that TRIM45 expression was downregulated in human glioma tissues." (PMID 28542145, 2017). "The reduced expression of TRIM45 in glioma was further confirmed by immunohistochemistry staining of normal brain tissue sections and tumor tissue sections." (PMID 28542145, 2017). "We next performed a colony formation assay in soft agar to evaluate the effect of TRIM45 on anchorage-independent growth in glioma cells." (PMID 28542145, 2017). "Here we report that TRIM45 expression is reduced in glioma tissues, and TRIM45 suppresses proliferation and tumorigenicity in GBM cells in vivo and in vitro." (PMID 28542145, 2017). "TRIM45 mRNA was significantly downregulated in glioma samples compared with normal brain tissue samples." (PMID 28542145, 2017). "TRIM45 mRNA levels were lower in high-grade (WHO grade III/IV) gliomas compared with low-grade (WHO grade I/II) gliomas." (PMID 28542145, 2017). "To determine the functional and clinical relevance of TRIM45 in human glioma, we first examined TRIM45 expression levels in normal brain tissues and human primary glioma tissues using quantitative real-time PCR (qRT-PCR) and immunoblot assays." (PMID 28542145, 2017). "To investigate the function of TRIM45 in the progression of glioma, we established U87 MG (referred to as U87) and LN229 glioma cell lines stably overexpressing Flag-tagged TRIM45." (PMID 28542145, 2017). "TRIM45 is downregulated in glioma tissues compared to a normal brain." (PMID 36139694, 2022). "Here, we report that TRIM45 expression is significantly reduced in glioma tissue samples." (PMID 28542145, 2017). "We subsequently investigated whether TRIM45 expression levels represented a distinct molecular signature for a subset of gliomas." (PMID 28542145, 2017). "Similar results were observed in TRIM45-knockdown glioma cells." (PMID 28542145, 2017). "However, little is known regarding the role of TRIM45 in cancer biology, especially in human glioma." (PMID 28542145, 2017).
glioma (continued). "To explore which signalling pathways were affected by TRIM45, we selected the GSE76328 dataset from the GEO database, which contained the mRNA expression of each gene in U251 cells (Human glioma cells) in the lv-TRIM45 transfection and negative control groups." (PMID 38037161, 2023). "We did not detect any change in the phosphorylation status of all the kinases examined, regardless of whether the expression of TRIM45 was upregulated or downregulated, suggesting that TRIM45 does not affect the PI3K/AKT, MAPK, and NF-κB signaling pathways in glioma cells." (PMID 28542145, 2017).
glioblastoma (5 papers, 2017 to 2025). The most malignant astrocytic tumor (WHO grade IV). "TRIM45 plays an inhibitory role in brain tumours, and overexpression of TRIM45 can inhibit the proliferation and tumorigenicity of glioblastoma cells in vivo and in vitro." (PMID 38037161, 2023). "Overexpression of TRIM45 suppresses proliferation and tumorigenicity in glioblastoma cells in vitro and in vivo." (PMID 28542145, 2017). "Overexpression of TRIM45 can inhibit glioblastoma cell proliferation." (PMID 40078998, 2025). "In addition, CRISPR/Cas9-mediated knockout of TRIM45 promotes proliferation and inhibits apoptosis in glioblastoma cells." (PMID 28542145, 2017).
breast carcinoma (3 papers, 2013 to 2023). "In a large-scale gene expression array analysis conducted in breast cancer samples from Taiwanese women, TRIM45 expression was diminished." (PMID 32290274, 2020). "Furthermore, TRIM45 was highly positively correlated with clinical indicators ER and PR in breast cancer." (PMID 37521466, 2023).
ischemic stroke (3 papers, 2022 to 2023). A stroke disorder caused by obstruction of blood flow to the brain, due to thrombotic (local blood clot formation) or embolic (due to a blood clot or other material traveling from another site) event. "More importantly, microglia-specific knockdown of TRIM45 in mice significantly reduced the infarct size, mitigated neurological deficit scores, and improved cognitive function after ischemic stroke." (PMID 35217833, 2022). "Collectively, these data suggest that TRIM45 expression is significantly upregulated after ischemic stroke and that activated microglia are the main source of upregulated TRIM45 expression." (PMID 35217833, 2022). "In this study, we found that ischemic stroke significantly upregulated TRIM45 expression in microglia." (PMID 35217833, 2022). "Other studies have shown that TRIM45 plays a role in ischaemic stroke." (PMID 38037161, 2023). "To further confirm whether TRIM45 knockdown could directly protect against neuronal death induced by ischemic stroke through microglial regulation, we transfected microglial cells with LV-TRIM45." (PMID 35217833, 2022). "Together, these findings suggest that TRIM45 functions as a novel signaling regulator in ischemic stroke injury and may be a promising approach to protect neuronal function against ischemic stroke-related injury." (PMID 35217833, 2022). "Specifically, TRIM45 expression was clearly upregulated in microglia after ischemic stroke." (PMID 35217833, 2022). "Therefore, an experimental stroke model was established by MCAO surgery, and qRT-PCR indicated that the TRIM45 mRNA levels increased at 6 h and reached a peak at 24 h after ischemic stroke." (PMID 35217833, 2022). "However, as TRIM45 is not only expressed in microglia, we cannot eliminate the possibility that the effect of TRIM45 on ischemic stroke originates from the cooperative effects of multiple cells in ischemic tissue, including several cell types, such as neurons and astrocytes." (PMID 35217833, 2022). "Herein, Trim45 might represent a promising therapeutic target for the treatment of ischemic stroke." (PMID 35217833, 2022).
brain tumors (2 papers, 2023). "Likewise, TRIM45 also acts as a tumor suppressor in brain tumors and non-small cell lung cancer." (PMID 37521466, 2023).
breast tumors (1 paper, 2020). "Low BRCA1 expression in cells along with BRCA1 inactivation in breast tumors is associated with reduced expression of CCNL2, DBF4B, and TRIM45." (PMID 32290274, 2020). "Here, the translational control of TRIM45 by BRCA1 that leads to low TRIM45 levels in BRCA1-deficient breast tumors, may represent a novel mechanism contributing to the onco-suppressive role of BRCA1." (PMID 32290274, 2020). "Given the functional implications of BRCA1 inactivation on the translation of ADAT2, CCNL2, DBF4B, and TRIM45, we wondered whether the levels of these proteins were correlated to BRCA1 status in breast tumors." (PMID 32290274, 2020).
Cerebral ischemia (1 paper, 2022). Restriction of arterial blood supply to the brain associated with insufficient oxygenation to support the metabolic requirements of the tissue. "Here, we found that the TRIM45 protein was highly expressed in the peri-infarct areas of mice subjected to cerebral ischemia and reperfusion injury induced by middle cerebral artery occlusion." (PMID 35217833, 2022). "It is unclear whether TRIM45 also plays a role in microglial phagocytosis after cerebral ischemia." (PMID 35217833, 2022). "However, whether and how TRIM45 plays a role in cerebral ischemia remains to be investigated." (PMID 35217833, 2022). "Therefore, we speculated that TRIM45 knockdown protects against cerebral ischemia in vivo." (PMID 35217833, 2022). "However, the role of TRIM45 in cerebral ischemia remains unknown." (PMID 35217833, 2022).
Cognitive impairment (1 paper, 2023). Abnormal cognition is characterized by deficits in thinking, reasoning, or remembering. "Knocking down TRIM45 protected against neuronal damage and cognitive impairment in septic mice." (PMID 38037161, 2023). "Furthermore, we aimed to verify whether TRIM45 was related to cognitive impairment." (PMID 38037161, 2023). "This study was the first to show the role of TRIM45 in SAE and that it is important in alleviating cognitive impairment induced by SAE." (PMID 38037161, 2023). "Consistent with previous studies, intraperitoneal injection of LPS resulted in severe learning and memory impairment mice, as shown by the water maze test, and a lack of TRIM45 alleviated cognitive impairment in septic mice." (PMID 38037161, 2023).
colon cancer (1 paper, 2024). "In our study, no significant variation was noted in the protein expression levels of TRIM45 in early-stage colon cancer tissues." (PMID 39268080, 2024).
hepatocellular carcinoma (1 paper, 2024). A malignant tumor that arises from hepatocytes. "Our findings concur with one bioinformatic study in hepatocellular carcinoma that has established a significant correlation between TRIM45 expression and adverse prognosis." (PMID 39268080, 2024).
influenza (1 paper, 2025). An acute viral infection of the respiratory tract, occurring in isolated cases, in epidemics, or in pandemics; it is caused by serologically different strains of viruses (influenzaviruses) designated A, B, and C, has a 3-day incubation period, and usually lasts for 3 to 10 days. "Next, we analyzed the effect of siRNA-mediated knockdown of TRIM45 on the expression level of influenza PB2 by western blotting." (PMID 41129599, 2025). "Next, we detected the expression of LC3-II, an autophagosomal marker that reflects macroautophagic activity, in an experiment to examine the effect of TRIM45 on the stability of influenza PB2." (PMID 41129599, 2025). "Therefore, we examined the effect of TRIM45 on the level of influenza PB2 by introducing NH4Cl, an inhibitor of the autophagy lysosomal pathway, which is known to neutralize the acidic lysosomal pH." (PMID 41129599, 2025). "We then determined the effect of TRIM45 on the expression of PB2 during influenza infection." (PMID 41129599, 2025). "In this study, we found that TRIM45 promotes the degradation of influenza PB2 through autophagy, but without activation of the macroautophagy pathway." (PMID 41129599, 2025). "The expression of TRIM45 is induced upon influenza infection, and the pathogenicity of the PB2-Q602A mutant virus is significantly enhanced in mice, revealing the biological significance of TRIM45 and the CMA pathway in limiting the replication and virulence of influenza virus." (PMID 41129599, 2025).
liver cancer (1 paper, 2022). An epithelial or non-epithelial malignant neoplasm that arises from the liver. "Our results indicated that the increased expression of TRIM28, TRIM37, TRIM45, and TRIM59 in liver cancer tissues likely plays a pivot role in HCC." (PMID 35142083, 2022).
lung carcinoma (1 paper, 2022). "TRIM45 was found to be against in the tumorigenesis of lung cancer by promoting cell apoptosis through activating p38 signal." (PMID 36474231, 2022).
malignant glioma (1 paper, 2017). A grade III or grade IV glioma arising from the central nervous system. "A more comprehensive understanding of the role TRIM45 has in the pathogenesis of malignant glioma may provide an opportunity to develop a novel therapeutic strategy by restoration of TRIM45 expression." (PMID 28542145, 2017).
Sepsis (1 paper, 2023). Sepsis is defined as life-threatening organ dysfunction caused by a dysregulated host response to infection. "Therefore, reducing brain levels TRIM45 may alleviate the brain damage caused by sepsis, and TRIM45 is one of the targets of sepsis." (PMID 38037161, 2023). "Therefore, reducing brain levels TRIM45 may alleviate the brain damage caused by sepsis, and TRIM45 maybe one of the targets of sepsis." (PMID 38037161, 2023). "The protein and mRNA levels of TRIM45 in peripheral blood mononuclear cells from sepsis patients were examined." (PMID 38037161, 2023). "Based on these results, we suggest that TRIM45 can be used as a regulatory protein or marker of sepsis." (PMID 38037161, 2023). "We extracted peripheral monocytes from patients with sepsis and analysed TRIM45 by PCR and WB." (PMID 38037161, 2023).
Stroke (1 paper, 2022). Sudden impairment of blood flow to a part of the brain due to occlusion or rupture of an artery to the brain. "Xing Li and co-workers at Huazhong University of Science and Technology, Wuhan, China, examined the role of the TRIM45 protein following stroke in mice." (PMID 35217833, 2022). "Given the increased expression of TRIM45 in microglia following stroke, we investigated the functional role of TRIM45 in the microglia-mediated inflammatory response." (PMID 35217833, 2022). "However, in the present study, we found that TRIM45 expression was strongly enhanced in the ischemic penumbra in a stroke model." (PMID 35217833, 2022). "The team found that stroke triggers the increase of TRIM45 expression in microglia." (PMID 35217833, 2022). "Moreover, the immunofluorescence results revealed that TRIM45 was increased after stroke in vivo." (PMID 35217833, 2022).
viral infections (1 paper, 2022). "Expression changes in UPS genes identified in both ST_EPN_RELA and PF_EPN_B included several differentially expressed UPS genes associated with interferon gamma signaling (MID1, PIAS1, TRIM2, TRIM22, TRIM45) that may promote a proinflammatory milieu similar to that observed upon viral infections." (PMID 36293188, 2022).